MIR4505 (microRNA 4505)
Synonyms: hsa-mir-4505; mir-4505
Gene: MicroRNA gene on chromosome 14 (73,758,747 to 73,758,819, forward strand). Ensembl gene ENSG00000264741.
Diseases named in the same sentence as MIR4505 in open-access papers:
MIR4505 is named in the same sentence as 1 disease in open-access papers, as found by Europe PMC text mining. Sharing a sentence is not in itself a finding about the gene and the disease.
MIR4505 shares sentences with these, for which no sentence is quoted: lung carcinoma (1 paper).